CCL2 (C-C motif chemokine ligand 2)
Diseases named in the same sentence as CCL2 in open-access papers (continued):
Sharing a sentence is not in itself a finding about the gene and the disease.
tumor (continued). "For example, using C–C chemokine 2 (CCL2) to block the recruitment of tumor-associated macrophages/microglia, or the colony-stimulating factor-1 (CSF-1R) inhibitor to impair the survival of macrophages/microglia." (PMID 38238749, 2024). "In the present study, we found the upregulation of the CCL2 gene, encoding a chemokine ligand that exerts chemotactic activity while favoring the recruitment of macrophages to the tumor." (PMID 39456647, 2024). "More specifically, CDYL knockdown evoked the influx of CCL2-recruited monocytes/macrophages and M1-like TAMs (tumor-associated macrophages/microglia) with antitumor activities." (PMID 39519018, 2024). "CCL2 facilitates the polarization of macrophages towards the M2 phenotype, which is associated with tumor growth stimulation by engaging the CC2 chemokine receptor (CCR2) from the macrophage surface." (PMID 39457618, 2024). "In a murine model of HCC, CCL2 secreted by senescent cells, is implicated in the recruitment of MDSCs, which, in turn, inhibit NK cell function, creating a pro‐tumour environment." (PMID 39270064, 2024). "CXCL10 (IP-10) and CCL2 (MCP-1) were both found to have significant associations with higher tumor burden in the E0771 ICI monotherapy study and the combined E0771 and 4T1 groups treated with anti-PD-1." (PMID 39623404, 2024). "Tumor associated macrophage showed significant positive correlations with CCL2 (cor = 0.095, P = 3.41E−02*), CD68 (cor = 0.178, p = 6.79E−05*), and IL10 (cor = 0.219, p = 9.38E−07*)." (PMID 39030403, 2024). "In this study, we discovered that CCL2 is significantly overexpressed in ESCC tumor tissues, and its high expression is closely associated with advanced TNM staging and poor survival prognosis, confirming its oncogenic role in ESCC." (PMID 38769475, 2024). "CCR2-positive monocytes are attracted to the LUSC tumor microenvironment in response to signals from cancer-associated fibroblasts via CCL2, contributing to an immunosuppressive environment." (PMID 38962009, 2024). "In their 2021 study, Liu and colleagues discovered that CCL2 is the primary mediator released by tumor-associated adipocytes into the surrounding extracellular environment." (PMID 38970097, 2024). "It has already been shown that cancer-associated fibroblasts, which belong to the tumor microenvironment, secrete CCL2 and induce functional reprogramming of monocytes to immunoinhibitory myeloid-derived suppressor cells." (PMID 39199602, 2024). "In contrast to the previous study, in all patients and in tumor stage 2 patients, CCL2 positivity in TC was associated with shorter OS, while in the chemotherapy-treated patients, CCL2 positivity was associated with shorter OS and DSS." (PMID 38928033, 2024). "In this research, we developed a predictive model for patient outcomes using biomarkers associated with CCL2‐expressing tumour cells, leveraging a combination of data sources and a suite of computational methods." (PMID 39706820, 2024). "Tumor-associated microglia are drawn to the cancer site by chemokines such as CCL2, and help the tumor to expand and invade by secreting cytokines and growth factors such as IL-6, TGF-β, and VEGF." (PMID 38523646, 2024). "CCL2 is a key chemoattractant for tumor-associated macrophages, promoting vascularization, with prior links to CRC progression and antiangiogenic therapeutic resistance." (PMID 38697618, 2024). "Among other notable DEGs, PD-L1+ clusters were also defined by high expression of many transcripts encoding for chemokines that have been shown to be released by suppressive tumor-associated neutrophils such as Ccl2, Ccl3, Ccl4, Ccl5, Ccl12, Ccl17, and Cxcl16." (PMID 39392875, 2024). "Tumor-associated neutrophils expressing CCL2+ or CCL17+ promote BMP-2 and TGF-β2 secretion, thereby enhancing miR-301b-3p expression via paracrine signaling and activating the NF-κB signaling pathway." (PMID 38694506, 2024).
tumor (continued). "Analysis of patient tumor samples revealed that overall lung tumor NF-κB activity fosters T cell infiltration, attributable to the downregulation of chemokine ligand 20(CCL2)expression linked with tumor growth." (PMID 39493763, 2024). "Tumor-associated macrophage markers showed positive correlations, with CCL2 (R = 0.190, P = 1.90E−05*) and CD68 (R = 0.340, P = 6.70E−15*)." (PMID 39030403, 2024). "CCL2 from primary tumors induces the recruitment of Ly-6C (+) monocytes, regulatory T (Treg) cells and tumor-associated macrophages (TAMs) to facilitate the invasion of CTCs into PMNs for colonization at distant sites." (PMID 38495881, 2024). "Pro-tumor factors that cause immunosuppression in the tumor microenvironment, such as CCL2, CCL5, neutrophil elastase (NE), and cathepsin G (CG), are expressed more often in N2 neutrophils, along with a greater expression of arginase." (PMID 39090094, 2024). "At the same time, enhances EIF4A3 and CCL2 expression via positive feedback, induces cSERPINE2 production, and further recruits tumor‐associated macrophages in breast cancer." (PMID 39584047, 2024). "In ESCC, it has been shown that HOXA7 induces tumor-associated macrophage infiltration and M2 polarization by promoting CCL2 secretion." (PMID 39596630, 2024). "Multiple studies show CCL2 recruits monocytes to BM-PCa tumors and increases the number of tumor-associated osteoclasts, such that CCL2 inhibition decreases tumor-induced bone resorption in mice." (PMID 37025604, 2023). "CCL2 is highly expressed by tumor-associated macrophages (TAM) in the tumor stroma, and substantial TAM accumulation is associated with disease recurrence and a poor prognosis." (PMID 37373025, 2023). "Several TAM-secreted chemokines, including CCL2/7, have been identified to be associated with tumor progression." (PMID 36693067, 2023). "MB49 cells also secrete CCL2, which promotes M2 polarization of tumor associated macrophages (TAM) after stimulation with radiation." (PMID 37569686, 2023). "Radiation can cause tumor cells to release chemokines and growth factors, such as CCL2, CCL7, and CSF-1, that are important for MDSC recruitment in the TME." (PMID 37208386, 2023). "CCL2 expressed by tumors also correlates with the immune infiltration of tumor-associated macrophages (TAMs) in many tumors and is associated with poor tumor patient prognosis, including in breast cancer." (PMID 37895310, 2023). "Our data show that lack of TNC expression causes an increasingly less sustained CCL2 synthesis in NT193 tumor cells." (PMID 37176074, 2023). "In contrast, knockdown of EZH2 resulted in DNA demethylation and subsequent upregulation of miR-124-3p levels, which inhibited the expression of its target CCL2 in tumor cells, causing arrest of M2 polarization of TAMs." (PMID 37208442, 2023). "Previous studies also have shown that CCL2 is able to promote tumor progression by recruiting and reprogramming tumor-associated macrophages, which accelerate tumor proliferation and metastasis by inducing immune escape." (PMID 38057698, 2023). "Among these cancer types, tumor-associated macrophage (TAM) markers such as CCL2, CD68, CD80, and IL10 had strong or moderate correlations with NNMT expression." (PMID 36817086, 2023). "PTX3 deficiency further leads to the up‐regulation of CCL2 expression and promotes tumour recruitment of macrophages." (PMID 36872292, 2023). "We analyzed the association between the level of tumor CCL2 mRNA expression and patient prognosis using the existing microarray or RNA-seq database (Kaplan‒Meier Plotter)." (PMID 37208442, 2023). "In primary tumors, a high frequency of CD14+ cells and a high level of CCL2 by tumor epithelial cells were associated with early recurrence." (PMID 37208442, 2023).
tumor (continued). "The increased CCL2 is secreted into the tumor microenvironment, promoting the recruitment of tumor associated macrophages (TAM), and then promoting lymphatic metastasis through the secretion of vascular endothelial growth factor C (VEGF-C)." (PMID 37907984, 2023). "Increased levels of CCR2 and its ligand CCL2 promote tumor growth, are associated with inflammation, advanced cancer, and predicts prognosis and recurrence due to their role in the tumor microenvironment." (PMID 37629186, 2023). "We then analyzed the effect of endothelial loss of CCL2 on tumor cells and endothelial cells in the co-culture model." (PMID 36374225, 2023). "CXCR2 ligands directly recruit neutrophils, which secrete CCL2 and cause monocyte recruitment to the tumor niche." (PMID 37686093, 2023). "In PDAC, it has been reported that CCL2 derived from Schwann cells facilitates the differentiation of monocytes into tumor-associated macrophages." (PMID 38099290, 2023). "The characteristics of tumor-associated M2 macrophages are orchestrated by the action of IL-4, IL-10, IL-13, macrophage colony-stimulating factor 1 (CSF-1), CCL2, or VEGF-A." (PMID 38033495, 2023). "PEGylated NOX-E36 binds the chemokine CCL2 thereby preventing the infiltration of CCR2-dependent tumor associated macrophages that initiate tumor-supporting angiogenesis." (PMID 36798121, 2023). "CCL2 promotes the recruitment of tumour-associated macrophages (TAMs) and increases the invasive properties of cancer cells, thereby promoting metastasis to the lungs and bone." (PMID 37108548, 2023). "Tumor-associated macrophages (TAM), a suppressive type of macrophage closely related to M2 macrophages, derive from tumor-associated monocytes that migrate to tumors via CCL2 and CCL3 gradients." (PMID 36167831, 2023). "Carboplatin-treated CAFs also upregulated the chemoattractant Ccl2, which has been associated with promoting monocyte and macrophage infiltration of the tumor site, and Irf1 and IL-1ß, which enhance M1 polarization in macrophages." (PMID 37660083, 2023). "On the other hand, other chemokines are associated with the infiltration of tumor sites by myeloid-derived suppressor cells (MDSCs), including CCL2 and CXCL8 (IL-8)." (PMID 37111629, 2023). "CCL2 induces recruitment and activation of TILs at the tumor site eventually causing an improved trastuzumab-immune-mediated anti-tumor activity." (PMID 37553381, 2023). "We then assessed the impact of PARP inhibition using Olaparib on CD47 expression and CCL2 expression (known to be up-regulated by chemotherapy and recruit tumor associated myeloid cells)." (PMID 37468567, 2023). "CCL2 has been associated with a variety of tumor-promoting processes, such as the recruitment of TAMs, and the promotion of tumor cell invasiveness." (PMID 37426676, 2023). "Tumor-associated macrophages (TAMs) signature gene CCL2 was highly expressed in TGCT compared with normal testicular tissue." (PMID 37352031, 2023). "Studies have shown that MDSCs (myeloid-derived suppressor cells) and TAMs (tumor-associated macrophages) are attracted and accumulated in the tumor site by CCL2." (PMID 37325423, 2023). "From these results, the authors proposed that high frequencies of CCL2+ tumor epithelial cells and CD14+ TAMs are significant risk factors for rapid tumor recurrence." (PMID 37208442, 2023). "Meanwhile, the expression of CCL2 by tumor cells is also regulated by Yes-associated protein (YAP)/TEA domain family member 4 (TEAD4) dependence." (PMID 37663266, 2023). "The expression of NUPR1 was highly correlated with tumor‐associated macrophage markers including CCL2, CCR5, CD80, and CD86." (PMID 36468653, 2023). "In conclusion, immunosuppression in the TME induced by 8 mg/kg smTRAIL was associated with smTRAIL-induced CCL2 secretion by tumor cells via the TRAIL-TRAILR axis." (PMID 37605148, 2023). "For instance, EGFR signaling has been implicated in promoting macrophage infiltration within the tumor, via the chemokine ligand 2 (CCL2)." (PMID 37759950, 2023).
tumor (continued). "Chemoattractant CCL2 overexpression has been linked to advanced tumor stages, metastatic disease conditions, and poor prognosis in CRC." (PMID 37525217, 2023). "Results show that C3AR1 has the strongest correlation with M2 macrophages (CD163, MRC1, CD209), tumor-associated macrophages (CCL2, CD86, CD68) and monocyte immune markers, including (CD14, CD33, ITGAX)." (PMID 37005667, 2023). "It is suggested that the pro-tumorigenic effects of CCL2 is a result of the chemoattractant properties of CCL2 in the recruitment of cells that suppress immune surveillance or recruit tumour-associated macrophages (TAMs) to tumour sites." (PMID 37108548, 2023). "In contrast, EZH2 depletion caused an miR-124-3p-dependent inhibition of CCL2 expression in the tumor cells, leading to the inhibition of M2 polarized activation." (PMID 36900330, 2023). "For example, sorafenib treatment increases intratumoral infiltrating of F4/80+ tumor-associated macrophages, CD4+CD25+FoxP3+ regulatory T cells, CCL2+/CCL17+ tumor-associated neutrophils and CD11b+Gr-1+ myeloid cells in human and murine HCC models." (PMID 36906597, 2023). "In this regard, the anti-tumorigenic actions of an anti-CCL2 compound (i.e., Bindarit) were reported in other tumor types, to prevent the infiltration of M2-tumor-associated macrophages and MDSCs into the tumor microenvironment." (PMID 36968588, 2023). "Cancer cells and mesenchymal stem cells (MSCs) secrete C-C motif chemokine ligand 2 (CCL2), a small protein that attracts tumor-associated macrophages (TAMs), which promotes malignant progression, such as drug resistance and metastasis." (PMID 36672395, 2023). "CAFs secrete cytokines such as TGF-β, IL-6, and CCL2, which promote the recruitment of monocytes and their differentiation into M2-type tumor-associated macrophages (TAMs)." (PMID 37165428, 2023). "In line with this, Mafb/Maf editing induced a strong regulation of M1-associated genes (Inos, Ccl2, and Tnfa) and concomitant downregulation of M2-associated genes (Fizz1, Arg1, and Mrc2) in KCs of tumor-bearing mice." (PMID 36821387, 2023). "This seems to be guided by chemokines such as CXCL12, CXCL10 and CCL2, produced by various cell types such as tumor cells, and tumor-associated macrophages and fibroblasts." (PMID 36766797, 2023). "We found that TCIPA triggers the recruitment of tumor-associated macrophages (TAMs) to lung metastases by secreting B16 cell-educated platelet-derived chemokines such as CCL2, SDF-1, and IL-1β." (PMID 37872588, 2023). "This is due to different mechanisms including the ability of CCL2 to recruit and regulate tumor-associated macrophages, which promote tumor progression and metastasis in part through its immunosuppressive role in the tumor microenvironment." (PMID 36374225, 2023). "It should be noted, however, that despite the established role of CCL2 in developmental and tumor-associated lymphangiogenesis, the exact molecular mechanism linking CCL2 activation with the enhanced VEGF-C expression remains to be elucidated." (PMID 37407839, 2023). "NLK directly interacted with STAT3 and decreased the CCL2 expression, inhibiting the recruitment of tumor-associated macrophages (TAMs) in the TME." (PMID 38008713, 2023). "This decrease in metastasis was caused by CCL2 inhibition reducing the production of CCL3 by immunosuppressive TAMs thereby reducing the ability of these macrophages to assist with tumor intravasation." (PMID 36249052, 2022). "Loss of EZH2 dramatically reduced CCL2 expression in the tumor cells, while EZH2 inhibitor conducted an opposite effect." (PMID 36038549, 2022). "For example, overexpression of lncRNA HOTAIR in HCC cell lines promoted CCL2 secretion, which is necessary for tumor-associated macrophages and recruitment of myeloid-derived suppressor cells." (PMID 36035299, 2022).
tumor (continued). "Pearson correlation analysis further showed that OPN was positively associated with M2 macrophage markers (CD163, VSIG4, MS4A4A, CX3CR1, and MRC1) and tumor-associated macrophage (TAM) markers (CCL2, CD68, and IL10)." (PMID 35669197, 2022). "Lineage Program 5 ECs are enriched in CSM1 and CCL2, two factors that can increase the recruitment of tumor-associated macrophages that facilitate vasculogenesis." (PMID 36185212, 2022). "In this research, the expression levels of tumor-associated macrophages (TAMs)-related markers (CCL2, CD68 and IL10) were a positive correlated PKIA expression, indicating an ontogenetic role of PKIA in HCC." (PMID 36204642, 2022). "For instance, C-C motif chemokine ligand 2 (CCL2) is upregulated in tumor cells following RT, and hence, leads to the corecruitment of tumor-associated macrophages, as well as Tregs, through the CCL2/chemokine receptor 2 (CCR2) axis." (PMID 36139006, 2022). "Tumor-associated macrophages (TAMs) have been reported to be associated consisting of highly expressed CCL2, CCL3, CCL5, CCL18, CXCL1, and CXCL12 in the TME." (PMID 35935996, 2022). "ACKR2-induced breast tumor inhibition results mainly from decoying inflammatory chemokines (e.g., CCL2), inhibiting vascular density, and suppressing tumor-associated macrophage infiltration." (PMID 35677043, 2022). "The researchers found that EE downregulated CCL2 expression in tumor cells and tumor-associated immune cells through the peripheral neuroendocrine–immune pathway sympathetic nervous system (SNS)/β-adrenergic receptors (β-ARs)/CCL2." (PMID 36077785, 2022). "Immune infiltration analysis revealed a significant difference in the proportion of immune cells in tumor and normal tissue, and the expression levels of C1R, CCL2, and TNFRSF1A were associated with immune cell infiltration of GBM." (PMID 35726234, 2022). "CCL2 is frequently overexpressed in tumor cells in the tumor microenvironment (TME) for recruiting tumor-associated macrophages (TAMs) to support tumor growth." (PMID 36358838, 2022). "For example, PDAC cells use the CCL2/CCR2 axis to recruit tumor-associated macrophages (TAMs) and myeloid-derived suppressor cells (MDSCs), and the CCL5/CCR5 axis to recruit regulatory T cells (Tregs)." (PMID 35205732, 2022). "The most protruding TME member in these cells is the tumor-associated macrophages (TAMs), which mediate tumor proliferation by secreting growth factors and inflammatory mediators such as CCL2, IL-1α, IL-6 and TNF-α and induce treatment resistance in cancer." (PMID 35736173, 2022). "Exotoxins increased the levels of C-C motif chemokine ligand 2, which aided tumor-associated macrophages (TAM) and cancer progression." (PMID 35865926, 2022). "Lurbinectedin has a direct effect on the tumor microenvironment by modifying the immune-regulatory properties of tumor associated macrophages, where it significantly inhibits the transcription of CCL2, CXCL8, and VEGF." (PMID 34739582, 2022). "On the contrary, EZH2 depletion led to DNA demethylation and subsequent upregulation of miR-124-3p level, which inhibited its target CCL2 expression in the tumor cells, causing arrest of TAMs M2 polarization." (PMID 36038549, 2022). "In particular, the differentiation and survival of tumor-associated macrophages (TAMs) depend on CCL2." (PMID 36077785, 2022). "The paracrine cytokines secreted by cancer-associated fibroblasts, such as TGFβ, CXCL12, CCL2 and IL-6, have been identified as important signaling molecules for tumor progression and immunosuppression in the microenvironment." (PMID 35628489, 2022). "CCL2 or CCL2-CCR2 axis is relevant in recruiting tumor-associated macrophages to the site of cancer." (PMID 35563446, 2022). "Chemokines have long been implicated in macrophage accumulation within tumours and their inhibitors, such as anti-CCL2 or CCR2 blockade, have been successfully tested in experimental tumours." (PMID 36439180, 2022).